ENSG00000274492 (novel transcript)
Gene: Long non-coding RNA gene on chromosome 14 (88,819,608 to 88,822,151, reverse strand). Ensembl gene ENSG00000274492.
Gene Ontology:
Molecular function: U6 snRNA binding
Biological process: formation of quadruple SL/U4/U5/U6 snRNP; spliceosomal tri-snRNP complex assembly
Cellular component: U4 snRNP; U4/U6 x U5 tri-snRNP complex